MGAM2 (maltase-glucoamylase 2 (putative))
Tractability: Small molecule: an approved drug acts on it; a high-quality ligand is known; it belongs to a druggable protein family. Antibody: UniProt predicts a signal peptide or a membrane-spanning region. PROTAC: a small molecule that binds it is known.
Gene: Protein-coding gene on chromosome 7 (142,111,718 to 142,222,324, forward strand). Ensembl gene ENSG00000257743.
Subcellular location: Membrane
Subcellular location (Human Protein Atlas): Vesicles; Cytosol
Gene Ontology:
Molecular function: alpha-1,4-glucosidase activity; carbohydrate binding; glucan 1,4-alpha-glucosidase activity; hydrolase activity, hydrolyzing O-glycosyl compounds
Biological process: carbohydrate metabolic process; disaccharide catabolic process
Cellular component: apical part of cell; membrane
Homologues: Orthologues: chimpanzee MGAM2 (99% identical), macaque MGAM2 (93% identical), pig MGAM2 (69% identical), dog MGAM2 (68% identical), mouse Mgam2-ps (63% identical), rat Mgam2 (62% identical), guinea pig MGAM2 (62% identical), tropical clawed frog mgam (41% identical), zebrafish gaa2 (15% identical), Caenorhabditis elegans aagr-2 (13% identical), Caenorhabditis elegans aagr-4 (9% identical), Drosophila melanogaster GCS2alpha (8% identical), and 2 more. Paralogues in human: MGAM (48% identical), SI (41% identical), GAA (15% identical), GANAB (9% identical), GANC (9% identical), MYORG (5% identical).
Diseases named in the same sentence as MGAM2 in open-access papers:
MGAM2 is named in the same sentence as 6 diseases in open-access papers, as found by Europe PMC text mining. Sharing a sentence is not in itself a finding about the gene and the disease. The quoted sentences say what the papers report.
inflammatory bowel disease (1 paper, 2024). A spectrum of small and large bowel inflammatory diseases of unknown etiology. "Among the commonly encountered genes during inflammation, MGAM2, which encodes maltase-glucoamylase 2, was reported in a study in inflammatory bowel disease as a member of a multi-gene set in blood reflecting inflammation in the gut." (PMID 39684365, 2024).
cancer (1 paper, 2025). A tumor composed of atypical neoplastic, often pleomorphic cells that invade other tissues. "ROC curve analysis was conducted to assess the diagnostic efficacy of MGAM and MGAM2 in various cancers." (PMID 40881483, 2025). "WES analysis conducted on patients with anal canal squamous cell carcinoma (ACSCC) revealed that MGAM2 ranks among the top three most commonly mutated genes in this uncommon form of cancer." (PMID 40881483, 2025). "The GSCA database also predicted a significant association between MGAM, MGAM2, and various cancer‐related pathways." (PMID 40881483, 2025). "To enrich our comprehension of MGAM's function, we broadened our research to encompass its lesser‐known variant, MGAM2, scrutinizing its differential expression across various forms of cancer." (PMID 40881483, 2025). "Following this, we delved into the implicated gene pathways and protein–protein interactions, assessing MGAM's and its paralog MGAM2's potential as a prognostic and diagnostic marker in cancer." (PMID 40881483, 2025). "As our understanding deepens through continuous research and the identification of specific genetic variants like rs2960746, the potential of MGAM and MGAM2 in revolutionizing cancer care becomes even more apparent." (PMID 40881483, 2025). "MGAM2 has been linked to cancers associated with the carbohydrate metabolism pathway." (PMID 40881483, 2025). "Using RNA‐Seq data from Recount3, Firebrowse, and gene set co‐expression analysis databases, we analyzed the differential expression of MGAM and its paralog MGAM2 across 33 cancer types." (PMID 40881483, 2025). "In light of the comprehensive analysis of MGAM and MGAM2 gene expressions within various cancer contexts, it is clear that these genes represented pivotal players in the complex nature of cancer biology." (PMID 40881483, 2025). "Our investigation into the role of MGAM and MGAM2 genes in various cancers has unveiled intriguing insights into their correlation with immune cell infiltration and their potential as diagnostic and prognostic markers." (PMID 40881483, 2025). "In conclusion, our investigation provides robust evidence supporting the critical function of the MGAM and MGAM2 genes in cancer biology." (PMID 40881483, 2025). "MGAM and MGAM2 showed differential expression across multiple cancers, with MGAM2 upregulated and MGAM downregulated in gastrointestinal tumors." (PMID 40881483, 2025). "Furthermore, MGAM and MGAM2 were identified as targets of approved antidiabetic drugs, adding another layer to their multifaceted roles in cancer biology and therapeutics." (PMID 40881483, 2025). "Interestingly, the expression pattern of MGAM and MGAM2 seems to be similar in cancers such as DLBC, KIRC, LUAD, and THYM, whereas it seems to have a converse effect in GI cancers such as COAD, READ, CHOL, ESCA, LIHC, and STAD." (PMID 40881483, 2025). "The identification of MGAM2 and other ER resident proteins, such as ERV1 homologs (EHVs), has implications for cancer immunotherapy and the treatment of BLBCs." (PMID 40881483, 2025).
MGAM2 also shares sentences with these, for which no sentence is quoted: colorectal cancer (1 paper); diabetes (1); gastrointestinal tumors (1); Sepsis (1).